CXCL8 (C-X-C motif chemokine ligand 8)
Diseases named in the same sentence as CXCL8 in open-access papers (continued):
Sharing a sentence is not in itself a finding about the gene and the disease.
tumor (continued). "So, in this study, SB225002, as a CXCR2 antagonist, may also block the effect of CXCL6, CXCL8 on the communication between OS cells and tumor microenvironment, which needs to be evaluated in our future research." (PMID 30984000, 2019). "Thus, in addition to a direct anti-tumor effect (induction of cell death), phenformin also exerts indirect anti-tumor effects through a modification of the chemokine milieu within the tumor microenvironment (e.g. inhibition of CXCL8 secretion)." (PMID 31741708, 2019). "In addition, in colorectal cancer patients, tumor-infiltrating NK cells also release high levels of vascular endothelial growth factor and CXCL8 to promote angiogenesis and tumor growth." (PMID 31781671, 2019). "We demonstrated key roles for Notch family members not only in inducing the expression of pro-metastatic chemokines such as CXCL8, but also in activating migratory and invasive capacities in the tumor cells upon their interactions with stromal cells in the presence of pro-inflammatory signals." (PMID 31105691, 2019). "CXCL8-positive cases were positively correlated with gender (p = 0.0346), T grade (depth of tumour invasion: p < 0.0001), N grade (degree of lymph node metastasis: p < 0.0001), M grade (degree of distant metastasis: p = 0.0187) and tumour stage (p < 0.0001)." (PMID 31147602, 2019). "However, due to the non-specific nature of this chemokine, further research is needed to clarify the usefulness of CXCL-8 as a tumor marker of OC." (PMID 30820705, 2019). "MSC/fibroblast-derived chemokines, including murine CXCL1 and CXCL2 (counterparts of human CXCL8), CCL2 and CCL5 were associated with recruitment of neutrophils, tumor-associated macrophages and myeloid-derived suppressor cells to TNBC tumors, where they promoted disease course." (PMID 31031757, 2019). "However, in TNFα-stimulated co-cultures, p65-regulated CXCL8 expression was partially contributed by MSCs, even though most of the p65-induced CXCL8 expression was contributed by the tumor cells (Figure 3B2)." (PMID 31105691, 2019). "Neutrophils secrete CXCL8 after stimulation with different cytokines released from the tumor." (PMID 30680411, 2019). "It has also been suggested that activation of NF-κB is associated with inflammatory signaling and tumor development, such as upregulation of COX-2 and nitric oxide synthase; up-regulation of the inflammatory cytokines IL-6, IL-8, and TNF-a; and upregulation of the chemokines CCL2 and CXCL8." (PMID 31266188, 2019). "In this regards, the results of the present study suggest that at least some of the anti-cancer effect of PLX4720 might be exerted also through a reduction of CXCL8 within the tumor microenvironment." (PMID 30867499, 2019). "Hypothetically, tumor sEV CXCL8 mRNA content might be adapted to serve as a useful biomarker for tumor senescence and monitoring potential for relapse during periods of remission." (PMID 30870978, 2019). "CCL2, CCL11, CCL16, CCL18, and CXCL8 promote tumor angiogenesis and endothelial cell survival." (PMID 30894861, 2019). "In addition, the differences between serum CXCL-8 levels and the depth of tumor invasion (T factor) were significant (p = 0.041)." (PMID 30820705, 2019). "Spearman’s correlation indicated that there was a significant correlation between serum CXCL-8 concentrations, depth of tumor invasion (T factor) (p = 0.010) and CRP concentrations (p = 0.003), while a positive correlation existed between SCC-Ag concentrations and TNM stage (p = 0.030)." (PMID 30820705, 2019). "Inflammatory CC (CCL2, CCL3, CCL5) and CXC (CXCL1, CXCL2, CXCL5, CXCL6, and CXCL8) chemokines recruit at the tumor site CCR2+ monocytes and CXCR2+ neutrophils that differentiate into tumor associated macrophages (TAMs) and tumor associated neutrophils (TANs), exerting pro- or anti-tumoral role." (PMID 30894861, 2019).
tumor (continued). "Moreover, in the present paper we assessed serum CXCL-8 levels in relation to the clinicopathological features of OC and proved statistically significant differences between serum CXCL-8 levels and depth of tumor invasion (T factor)." (PMID 30820705, 2019). "Interestingly, the Notch-mediated tumor-stroma-inflammatory network promoted tumor invasiveness and secretion of the chemokine CXCL8." (PMID 31681564, 2019). "However, we demonstrated significant differences between serum CXCL-8 levels and depth of tumor invasion (T factor)." (PMID 30820705, 2019). "However, due to the non-specific nature of this chemokine, further research is needed to clarify the usefulness of CXCL-8 as a potential tumor marker of OC." (PMID 30820705, 2019). "C-X-C motif chemokine ligand 8 (CXCL8) is involved in tumor proliferation, migration, and invasion." (PMID 32038715, 2019). "In addition, CXCL8 was found positively correlated with strong tumor lymphocytes infiltration (p = 0.0125), and decreased overall survival (p = 0.009)." (PMID 30883740, 2019). "The CXCL8 and IP-10 exert anti-tumor effects in the tumor migratory microenvironment." (PMID 31417646, 2019). "CXCL1, CXCL2, and CXCL8 have known tumor-supportive functions." (PMID 30870978, 2019). "CXCL-8 has been classified as neutrophil chemoattractant, but it may also play a role in tumor progression via the regulation of angiogenesis, growth, proliferation and survival of malignant cells, including OC." (PMID 30820705, 2019). "Moreover, the findings obtained with DAPT were recapitulated when Notch1 was knocked-down in the tumor cells by siRNA; in these experiments, Notch1 siRNA has led to similar reduction in TNFα-induced contact-dependent induction of CXCL8 as did DAPT." (PMID 31105691, 2019). "APS-modulated translation may also be aberrantly upregulated in a subset of tumour cells, leading to the overexpression of pro-oncogenic genes such as CXCL8." (PMID 30969964, 2019). "The aim of the current study was to measure serum concentrations of chemokine CXCL-8 in OC patients and establish whether this protein might be considered a potential candidate for a tumor marker in the diagnosis and progression of OC." (PMID 30820705, 2019). "Moreover, in the absence of TNFα stimulation, basal p65 activation mainly in the tumor cells has induced Notch1 activation (Figures 9A1,C1), which then contributed to a contact-dependent induction of CXCL8." (PMID 31105691, 2019). "However, to date, our study provides the first mechanistic information on the regulation of CXCL8 by Notch1 in the tumor-stroma-inflammation network." (PMID 31105691, 2019). "Indeed, CXCL8 is a chemokine with extensively described pro-tumorigenic effects which include influencing of tumor cell growth, angiogenesis, invasiveness and EMT16,20,35,36." (PMID 30867499, 2019). "They demonstrated that the expression of CXCL8 was upregulated in the invasion front of the tumor and that shRNA-mediated knockdown of CXCL8 resulted in significantly decreased cell proliferation, migration, and invasion in vitro and dramatic reduction of tumor metastasis in vivo." (PMID 30691207, 2019). "Moreover, upon CXCL8 down-regulation, the migration-relevant morphology of the tumor cells was partly reversed, and the migration and particularly the invasion potentials of the tumor cells were significantly reduced." (PMID 31031757, 2019). "If we consider the relationship between serum concentrations of the tested proteins and the histological type of OC, CXCL-8 levels, similarly to those of the classical tumor markers and CRP, were significantly higher in patients with OSCC in comparison with subjects with OAC." (PMID 30820705, 2019). "Furthermore, CXCL8 secreted by tumor and Treg cells has been shown to sustain MDSC migration and degranulation via CXCR1 and CXCR2 signalling to support cancer dissemination." (PMID 30591657, 2018). "Xenograft tumor tissue from A549 cell was used to test the specificity of anti-CXCL8 antibody." (PMID 29636079, 2018).
tumor (continued). "Additionally, the oncolytic adenovirus, dl922–947 was shown to modulate tumor microenvironment by decreasing IL-8/CXCL8 and MCP-1/CCL2 expression which resulted in compromised angiogenesis and macrophage infiltration." (PMID 30352606, 2018). "The role of CXCL8 and its homologs in recruiting neutrophils to established tumors has been demonstrated in various Ras-driven cancer models, however its role in recruiting neutrophils to tumor-initiating cells and the role of specific receptors is unclear." (PMID 30185911, 2018). "NT can also indirectly influence tumor angiogenesis through IL-8/CXCL8." (PMID 29467963, 2018). "Increased release of Cxcl8 from Pten-deleted tumor cells augmented the sensitivity and responsiveness of tumor cells to stromal chemokines by concurrently inducing the upregulating of chemokine receptors on tumor cells and inducing stromal chemokine production." (PMID 29946544, 2018). "Besides, CXCL8 level showed an upward trend with the increase of tumor size (p = 0.0128 and p = 0.0102)." (PMID 29636079, 2018). "Consequently, patients diagnosed as ADC showed elevated protein abundance of CXCL8 in tumor tissues and the peripheral circulation." (PMID 29636079, 2018). "In parallel, we performed immunohistochemistry for CXCL8 on the same tumor samples." (PMID 29560130, 2018). "Similarly, in a mice model of malignant mesothelioma, targeting CXCL8 by a neutralizing monoclonal antibody (mAb) decreased tumor progression." (PMID 29977225, 2018). "Based on these results, we hypothesized that the levels of mature miR-20a and CXCL8 protein are reliable indicators for the pro-tumor promoting activity of the interstitial fibroblasts." (PMID 29560130, 2018). "In all but one tumor cell line we could demonstrate a significant up to 75-fold higher expression of CXCL8 as compared to HEK." (PMID 30266096, 2018). "In addition, paracrine CXCL8/IL8 signalling facilitate changes in the composition of the tumor microenvironment." (PMID 30126117, 2018). "Then, we detected the CXCL8 expression on tumor tissues by IHC." (PMID 29636079, 2018). "Neutrophils, attracted by CXCL8, might affect tumor development in two discrete ways depending on their phenotype." (PMID 29850390, 2018). "Moreover, CXCL8 stimulation of PCa cells was described to regulate cyclin D1 expression, supporting cell cycle progression and PCa tumor growth." (PMID 29808619, 2018). "Relative neutrophilia increases the number of inflammatory factors such as pro-angiogenic factor (VEGF), growth factor (CXCL8), and anti-apoptotic factor (NF-κB) which may establish a tumor microenvironment and promote tumor growth and progression." (PMID 29089030, 2017). "CXCL8 promotes tumor progression through regulating construction of tumor microenvironment." (PMID 29147073, 2017). "CXCL8 recruits leukocytes, such as monocytes and neutrophils, into tumor microenvironment." (PMID 29147073, 2017). "We hypothesized that the anticancer properties of metformin are, at least partially, based on inhibition of tumor microenvironment construction through suppressing CXCL8 expression." (PMID 29147073, 2017). "In vivo studies revealed that suppression of CXCL8 expression leads to tumor regression." (PMID 29147073, 2017). "For either scenario, there exists the possibility of CXCL8 promoting the growth of the tumor." (PMID 28881576, 2017). "In cancer, CXCL8 promotes tumor cell proliferation and migration, angiogenesis, and metastasis." (PMID 29147073, 2017). "Examples of key players of cancer-related inflammation (CRI) include tumor-infiltrating lymphocytes, tumour-associated macrophages (TAMs), the secretion of cytokines such as TNF, IL-1, IL-6, and chemokines such as CCL2 and CXCL8, in addition to the occurrence of tissue remodeling and angiogenesis." (PMID 27555866, 2016). "For example, IL-8 (CXCL8) promotes tumor growth, angiogenesis and metastasis." (PMID 27834814, 2016).
tumor (continued). "In addition to the definition of several autocrine functions, CXCL8 has the potential to register profound effects on the tumor microenvironment, predominantly through angiogenesis or driving chemotactic migration of immune cells." (PMID 26799286, 2016). "In addition, ATC cells produce the chemokine IL-8/CXCL8 (hereafter IL-8) that is involved in several aspects of tumor biology, namely cell proliferation, cell survival, epithelial-to-mesenchymal transition, stemness, and also angiogenesis." (PMID 26625205, 2016). "The interconnection between inflammation and angiogenesis is explained by the ability of VEGF and chemokine such as CCL2 and CXCL8 to recruit leukocytes at the tumor site that in turn produce VEGF and inflammatory mediators and thus amplify tumorigenic signal via an autocrine and paracrine loop." (PMID 26859579, 2016). "Recently, we reported that TAM in PTC facilitated tumor metastasis through releasing CXCL8 and may target CXCR1/2 in tumor cells." (PMID 26875556, 2016). "High intra-tumoral expression of CXCL8 was confirmed by confocal analysis of tumor samples." (PMID 25806105, 2015). "CXCL8 (IL-8), an inflammatory chemokine originally discovered as the neutrophil chemoattractant and inducer of leukocyte-mediated inflammation, contributes to cancer progression through its induction of tumor cell proliferation, migration and angiogenesis." (PMID 25790431, 2015). "Therefore, increased CXCL8 production in the TME potentially contributes to tumour angiogenesis and cancer progression." (PMID 26465273, 2015). "Moreover, activating Ras mutation resulted in up-regulation of pro-angiogenic interleukin-8 (CXCL-8) leading to recruitment of endothelial cells, tumor vascularisation and tumor growth in vitro and more aggressive biological behavior in vivo." (PMID 25888291, 2015). "In recent years, it has also been shown that a link exists between CXCL8/IL-8 and tumor stemness." (PMID 26379707, 2015). "This latter result indicates that following their stimulation by TNFα, RasG12V-expressing cells secreted to the culture medium soluble factors that had pro-cancerous effects that promoted tumor growth, as was previously indicated by our in vitro analyses of CXCL8." (PMID 24598028, 2014). "We determined the effects of these factors on CXCL8 expression, using CXCL8 as a proxy for many pro-tumorigenic factors that may be induced in tumor cells." (PMID 24598028, 2014). "The evidence from our previous studies and others suggested that BTC play a critical role in the development of lung inflammation through the regulation of the cytokine secretion pattern and tumor cell progression through EGFR ligation, possibly associated with the over-production of CXCL8." (PMID 24629040, 2014). "Conversely, immature DC can increase the expression of VEGF and CXCL8 upon hypoxic challenge, which might exert pro-angiogenic function in the tumor microenvironment." (PMID 24782982, 2014). "Supporting a mechanism in which WT-Ras has been turned into an active entity, and in line with the fact that the MEK-Erk pathway mediates many of the Ras-induced activities, MEK-dependent pathways were involved in the ability of TNFα to induce CXCL8 expression in WT-Ras-expressing tumor cells." (PMID 24598028, 2014). "In addition to the CXCL8 axis, several chemokines have impacts on proliferation and survival of tumor cells." (PMID 24966464, 2014). "Hence, CXCL8 signaling is involved in regulating the communication between these cell types within the tumor microenvironment." (PMID 24224100, 2013). "CXCL8 promotes cancer cell proliferation, survival, and migration via its autocrine and paracrine activity, and it elicits an angiogenic response in endothelial cells and chemotaxis of neutrophils to the tumor site via its paracrine activity." (PMID 24224100, 2013). "Moreover, it has been shown that impeding neutrophil recruitment to the tumor site via CXCL8 or CXCR1/2 inhibition can reduce tumor growth in vivo." (PMID 24276377, 2013).
tumor (continued). "In addition to the local effects of these chemokines, metastasis of cancer cells is facilitated by CXCL8 and its receptors on tumor cells, which enables them to undergo the epithelial-mesenchymal transition, and then to migrate and seed at secondary sites." (PMID 24224100, 2013). "CXCL8 signaling may also be induced as a result of numerous environmental stresses within the tumor microenvironment including hypoxia, acidosis, hyperglycemia, cytotoxic chemotherapies and radiation." (PMID 24276377, 2013). "Notably, Bcl-2 acts as a signaling molecule by activating the NF-kB signaling pathway and inducing expression of CXCL1 and CXCL8 that in turn enhance the invasive phenotype of neighboring tumor cells." (PMID 24391922, 2013). "In addition to affecting the biology of the tumor cells themselves, activation of PPARγ also reduced production of the tumor cell-derived cytokines CXCL8, CXCL5, and CXCL1, which are critical for angiogenesis and tumor-stromal interactions." (PMID 22934105, 2012). "Conversely, antisense transfection of CXCL-8 in cancer cells inhibited multiple tumor activities." (PMID 23342280, 2012). "The Kaplan–Meier survival curve demonstrated that patients with positive CXCL8 staining in this tumour infiltrate had a significantly improved RFS (median survival not reached) compared with patients with negative staining (median survival 69 months; 95% CI: 37.7–100.3, P<0.001 log-rank test)." (PMID 21285972, 2011). "Instead, we postulate that the expression of CXCL8 may become detectable and especially significant in a more advanced disease stage, indicative of the tumour-promoting effects of the chemokine." (PMID 21285972, 2011). "Other findings suggest that CXCL1 or CXCL8 signalling may reduce tumour growth by promoting senescence through CXCR2." (PMID 21298036, 2011). "Interestingly, the removal of the tumor mass or suspected to be tumor mass (massive fibrosis) lowered the CXCL8 levels for PDAC, EC, and CP but only significantly for PDAC (P = 0.008)." (PMID 20214814, 2010). "Finally we investigated the impact of CXCL8 expression on tumour development in vivo by engrafting nude mice with wild type Ishikawa cells and FPS Ishikawa cells." (PMID 19819266, 2009). "To explore whether CXCL8 induced by FP receptor signalling could alter tumour growth in vivo we injected wild type Ishikawa (WT) cells or FPS cells subcutaneously into the dorsal flanks of nude mice." (PMID 19819266, 2009). "We found that CXCL8 expression was significantly elevated in FPS xenograft tumours compared with wild type tumours indicating that FP receptor was being activated by endogenous PGF2αin vivo similar to our observations using FPS cells and administering exogenous PGF2αin vitro." (PMID 19819266, 2009). "Immunohistochemical staining showed a significant reduction in the BrdU incorporation in the epithelial compartment of the mouse tumours in the animals engrafted with FPS tumour and treated with a CXCL8 neutralising antibody compared with FPS IgG controls (P < 0.001)." (PMID 19819266, 2009). "Lysophosphatidic acid (LPA), a phospholipid produced from malignant ovarian epithelium, can enhance the expression of CXCL8 by tumor cells and stimulate EOC cell invasion by enhancing membrane type-1 (MT1) matrix metalloproteinase (MMP) mediated activation of MMP2." (PMID 16824216, 2006). "Notably, CXCR2 serves as a key receptor for multiple chemokines (e.g., CXCL1, CXCL2, CXCL8) and is critically involved in the recruitment of myeloid-derived suppressor cells (MDSCs), a potent population of immunosuppressive cells, into the tumor microenvironment." (PMID 41347146, 2025). "However, some drugs targeting MM increase CXCL8 production, which may contribute to the promotion of certain neoplasm processes, chemoresistance of MM cells to treatment, and relapse of the disease." (PMID 40940985, 2025). "However, CXCL8 exerts various effects on disease prognosis and tumor immunity." (PMID 41432874, 2025).